RN7SL680P (RNA, 7SL, cytoplasmic 680, pseudogene)
Gene: Miscellaneous RNA gene on chromosome 20 (39,349,094 to 39,349,392, reverse strand). Ensembl gene ENSG00000275337.
Homologues: Orthologues: chimpanzee Metazoa_SRP (99% identical), macaque Metazoa_SRP (87% identical). Paralogues in human: RN7SL2 (85% identical), RN7SL1 (84% identical), RN7SL220P (83% identical), RN7SL3 (82% identical), RN7SL448P (82% identical), RN7SL803P (82% identical), RN7SL357P (81% identical), RN7SL778P (81% identical), RN7SL300P (81% identical), RN7SL60P (81% identical), RN7SL408P (81% identical), RN7SL441P (81% identical), and 702 more.